C6orf58 (chromosome 6 open reading frame 58)
Description:
May be involved in early liver development.
Synonyms: LEG1
Tractability: Antibody: UniProt places it where antibodies can reach, with medium confidence; UniProt predicts a signal peptide or a membrane-spanning region; its Gene Ontology location is reachable by antibodies, with medium confidence.
Gene: Protein-coding gene on chromosome 6 (127,519,455 to 127,591,820, forward strand). Ensembl gene ENSG00000184530.
Subcellular location: Secreted
Subcellular location (Human Protein Atlas): Cytosol; Vesicles; Nucleoplasm; Predicted to be secreted
Gene Ontology:
Molecular function: protein binding
Cellular component: extracellular exosome; extracellular region
Genetic constraint (gnomAD): Loss-of-function variants: 13 observed, 20.96 expected, observed/expected ratio (o/e) 0.62, 90% interval 0.4 to 0.99. The upper end of that interval is the gene's LOEUF score, 0.99, which puts it in group 4 of 6, group 1 being the genes least tolerant of losing a copy. Missense variants: 276 observed, 302.58 expected, observed/expected ratio (o/e) 0.91, 90% interval 0.83 to 1.01. Synonymous variants: 99 observed, 107.17 expected, observed/expected ratio (o/e) 0.92, 90% interval 0.78 to 1.09.
Homologues: Orthologues: chimpanzee C6H6orf58 (100% identical), macaque C4H6orf58 (92% identical), dog C6orf58 (64% identical), guinea pig C6orf58 (60% identical), mouse 2310057J18Rik (55% identical), rat Leg1 (53% identical), tropical clawed frog c5h6orf58 (34% identical), zebrafish C20H6orf58 (33% identical), zebrafish C20H6orf58 (32% identical).
Diseases named in the same sentence as C6orf58 in open-access papers:
C6orf58 is named in the same sentence as 9 diseases in open-access papers, as found by Europe PMC text mining. Sharing a sentence is not in itself a finding about the gene and the disease.
C6orf58 shares sentences with these, for which no sentence is quoted: glioma (2 papers); breast carcinoma (1); cancer (1); Hyperinsulinemia (1); malignant ovarian tumors (1); meningioma (1); nervous system disorder (1); Parkinson disease (1); tumor (1).